CAV1 (caveolin 1)
Diseases named in the same sentence as CAV1 in open-access papers (continued):
Sharing a sentence is not in itself a finding about the gene and the disease.
tumor (continued). "In this study we complexed fenretinide with Human Serum Albumin [HSA] with the aim to enhance its bioavailability through an improvement of its aqueous solubility and to exploit the Albumin affinity to cav-1 to favour the uptake of the complex in the tumor cells expressing high levels of cav-1." (PMID 25015569, 2014). "Apart from enhancing β1,6-branching in complex and hybrid N-glycans, caveolin-1 also up-regulates α-2,6-sialyltransferase I (ST6Gal-I) expression and then promotes the α2,6-sialylation of integrin, thus increasing tumor cell adhesion to extracellular matrix (ECM)." (PMID 24739808, 2014). "However, a higher incidence of Cav-1 expression has generally been found in patients with poorly differentiated tumors (higher Gleason score), positive surgical margins, high tumor stages (TNM T4), lymph node metastasis and poor tumor prognosis." (PMID 25202343, 2014). "Furthermore, numerous studies have suggested that Cav-1 serves as a negative regulator of cell proliferation or as a tumor suppressor." (PMID 25202343, 2014). "The theory that Cav-1 promotes the motility of tumor cells is well established." (PMID 25202343, 2014). "Additionally, these findings further require validation in biological tumor models using cell lines stably-transfected with BKCa/caveolin-1." (PMID 25397596, 2014). "Given that the downregulation of stromal Cav-1 results in autophagy, which is induced by the oxidative stress and hypoxia of the tumor microenvironment, this indicates that a feed-forward mechanism exists in the interactive association between Cav-1 and autophagy/mitophagy in CAFs." (PMID 25202343, 2014). "In summary, our results suggest that CAV1 could function as a potent tumor suppressor in ARMS tumors." (PMID 25313138, 2014). "Additionally, high vessel density (measured as expression of von Willebrand factor) and decreased tumor stromal expression of Caveolin-1 was related to bad prognosis." (PMID 24505269, 2014). "Combined expression of SRC kinase, ANXA1, CAV-1 and EphA2 was found in 31 % of tumour samples." (PMID 25594008, 2014). "The downregulation of Cav-1 is a major characteristic of CAFs and existing studies have indicated that CAFs have the ability to prevent cancer cell apoptosis, enhance the proliferation of cancer cells and stimulate tumor angiogenesis." (PMID 25202343, 2014). "The state of oxidative stress in the tumor microenvironment is triggered by lateral epithelial cancer cells and sustained through positive feed-forward control with the downregulation of stromal Cav-1." (PMID 25202343, 2014). "Therefore, in order to go deeply into the mechanism by which CAV1 delays tumor growth in ARMS we sought to analyze the effects of CAV1 expression on MAPK signaling." (PMID 25313138, 2014). "In addition, the expression of caveolin-1 and flotillin-1 staining was significantly increased along with the progression of tumor grades I to III." (PMID 25243186, 2014). "By three weeks post-injection, the tumor luminescence was strikingly higher in mice bearing Cav-1-overexpressing cells as compared to control cells, indicating the positive regulatory role of Cav-1 on tumor growth." (PMID 24939878, 2014). "Furthermore, we also verified that CAV1 knockdown not only can inhibit xenograft tumor growth and metastasis in HCCLM3 cells, but it had the same effect in the other HCC lines, such as MHCC97-H." (PMID 25180681, 2014). "In patients, CAV1 presence in tumours often correlates with a poor prognosis 18–22." (PMID 24500501, 2014). "Depending on the tissue of origin CAV1 can be a tumor suppressor or initiator." (PMID 25148256, 2014). "Moreover, similar to autophagy, CAV1 plays a dual role in cancer, functioning both as a tumor suppressor and promoter of tumor metastasis." (PMID 25328887, 2014).
tumor (continued). "To test our hypothesis we validated first the expression levels of CAV1 on a broader number of cell lines and in tumor samples." (PMID 25313138, 2014). "By contrast, studies have suggested that the upregulation of Cav-1 in HCC may serve as a tumor suppressor." (PMID 25202343, 2014). "Among them miR-199a is the only one found highly expressed in ARMS suggesting that this miRNA could be a good candidate as responsible for CAV1 downregulation in the tumor samples studied." (PMID 25313138, 2014). "CAV1's function as a tumor suppressor or promoter in HCC is still debated." (PMID 25180681, 2014). "The correlation between the expression of Cav-1 in various types of cancer cells and clinical characteristics, including tumor size, differentiation, tumor grade, tumor stage, hematogenous or lymph node metastasis, tumor prognosis and overall survival rate, has been clarified." (PMID 25202343, 2014). "Interestingly, we observed a remarkable tumor bioluminescence in mice bearing Cav-1-overexpressing cells after the dissection of subcutaneous tumors." (PMID 24939878, 2014). "Despite a number of contradictory Cav-1 studies, the majority of reports markedly suggest that Cav-1 represents an important cancer cell biomarker in carcinogenesis, differentiation, metastasis and tumor progression, and independently serves as a predictor of overall survival rate." (PMID 25202343, 2014). "The death predictive value of Cav-1 thresholds in tumor cells and in CAFs was analyzed as well." (PMID 23527097, 2013). "CAV1 silencing in EWS cells impairs tumor growth in nude mice." (PMID 23951165, 2013). "Correlation between tumor cells and CAFs in Cav-1 expression was also analyzed." (PMID 23527097, 2013). "The role of Cav1 in tumour onset and progression has been previously covered by several reports." (PMID 23521716, 2013). "According to this view, Cav1 could play a role as either a tumour suppressor gene or an oncogene, and the switch is likely governed by tumour stage and tumour temporal context." (PMID 23521716, 2013). "The precise role of caveolin-1 in tumorigenesis and whether the protein acts as a tumor suppressor or as an oncogene seems to be cell type and context-dependent." (PMID 23951165, 2013). "Of the samples that could be analysed for the combined expression of Cav-1 and pERK-1/2 we found 42% (66/158) of patient tumours were positive for Cav-1 and 35% (55/158) positive for pERK-1/2." (PMID 24119769, 2013). "Notably, patients whose tumours simultaneously expressed Cav-1 and pERK-1/2 had a DFS of only 3.33 yrs versus 6.17 yrs (P = 0.001) for tumours either negative for one or both of the biomarkers." (PMID 24119769, 2013). "Furthermore, we also observed the tumor by electron microscopy and investigated the expression of caveolin-1 by immunohistochemistry." (PMID 23714181, 2013). "The targeting of Cav-1 may represent a future strategy for the prevention and treatment of metastases or even micrometastasis before the development of overt secondary tumours." (PMID 24119769, 2013). "During the early stages of tumour progression, Cav1 negatively controls cell-cycle progression and restrains cell proliferation, whereas growing evidence suggests that Cav1 may induce more advanced cancer phases." (PMID 23521716, 2013). "In an attempt to resolve the conflicts between the biological and functional data, it has been suggested that in the early stages of cancer progression Cav1 restrains tumour growth, whereas in the advanced stages of disease, Cav1 has a pro-survival and tumour promoting role." (PMID 23521716, 2013). "In the epithelial compartment, Cav-1 impacts both positively and negatively on tumor development." (PMID 23527097, 2013). "A second article reported enhanced tumor promotion in caveolin-1 knockout mice as well." (PMID 24236206, 2013).
tumor (continued). "Our current studies in caki-1 cells (mRCC origin) show Cav-1 to be both pro-proliferative and pro-invasive, and may reflect the greater reliance of advanced and metastatic RCC tumours upon Cav-1 for their patho-biology." (PMID 24119769, 2013). "We also address the potential application of caveolin-1 in tumour therapy and diagnosis." (PMID 23521716, 2013). "However, the role of Cav-1 in malignancy is both complex and multifaceted with both tumour suppressor and oncogenic properties described in what appears to be a disease-specific and context-dependent manner." (PMID 24119769, 2013). "However, another study published in Cell reported contrary functions of CAFs Cav-1 protein that stromal Cav-1 favors tumor invasion and metastasis through force-dependent architectural regulation of the microenvironment." (PMID 23527097, 2013). "Roles of Cav-1 protein in tumor development are tumor-dependent and compartment-dependent." (PMID 23527097, 2013). "Cav1 plays a key role in cell signalling and in tumour progression towards the metastatic stage." (PMID 23521716, 2013). "Thus, in cancer models including prostate, breast and colon, caveolin-1 expression is known to be up-regulated and protein levels correlate with tumor progression and metastasis." (PMID 22505999, 2012). "Overall, caveolin-1 appears to have dual functions depending on the cell type: as a tumor suppressor by inhibiting anchorage-independent cell growth and as a promoter of tumor metastasis by preventing anoikis." (PMID 22505926, 2012). "To determine the cell types in which the proteins were differentially expressed, we performed immunohistochemical analyses for five molecules (ACC-pS79, CHK2, IGFBP2, cyclin B1, and caveolin 1) on samples that showed difference between normal and tumor tissues." (PMID 22348039, 2012). "The precise role of caveolin-1 in tumorigenesis remains a matter of intense debate and whether the protein acts as a tumor suppressor or as a promoter of metastasis seems to be cell type and context-dependent." (PMID 22505999, 2012). "It was interesting that two tumor suppressive genes, Cav1 and ST7, surrounded the Met locus." (PMID 22952676, 2012). "Interestingly, these pockets of Cav-1 cells were in close proximity to cells within the tumor expressing high levels of cytokeratin 5 or cytokeratin 14 which were frequently were associated with ghost cells." (PMID 22356861, 2012). "In the RST tissue sections, Cav-1 protein could be detected at moderate or high levels in the tumor cells themselves." (PMID 22356861, 2012). "Taken together, these data suggest that Cav-1 may play anti-angiogenic role in a murine LLC model of tumor-induced angiogenesis." (PMID 26605130, 2012). "Therefore, most of the tumor cells in PMTs express low levels of Cav-1 however, pockets of tumor cells expressing high levels of Cav-1 can be found within some of these tumors." (PMID 22356861, 2012). "Furthermore, autophagy also promotes tumor development synergistically with Cav-1 degradation through the metabolic/catabolic reprogramming of CAFs to fuel the growth of adjacent tumor cells." (PMID 23203033, 2012). "Our group became interested in Cav-1 following the analysis of DNA microarray results that compared mammary tissue from wild type mice to tumor tissue from transgenic mice that express elevated levels of the type I insulin-like growth factor receptor (IGF-IR) in mammary epithelial cells." (PMID 22356861, 2012). "In summary, the cav-1 mRNA level is down-regulated in tumor samples of NSCLC." (PMID 22200856, 2012). "Cav-1 influences tumor progression not only in cancer cells but also in tumor stroma." (PMID 23203033, 2012). "Moreover, treatment with cell-permeable CSD peptide prevented increased tumor microvessel permeability and tumor growth in Cav-1 KO mice." (PMID 26605130, 2012). "Therefore, the physiological role of CAV1 in cancer cells is quite complicated depending e.g. on the type of cancer and the tumor origin." (PMID 22152020, 2011).
tumor (continued). "However, caveolin-1 regulation impacts both negatively and positively on several aspects of tumor progression." (PMID 21660237, 2011). "Therefore, our data encourage further investigations to enlighten the role of CAV1 in tumour progression and to assess its function as prognostic marker for clinical use in serum and/or urine." (PMID 22152020, 2011). "Caveolin-1, also known as a tumor-suppressor factor, inhibits a number of proliferative pathways." (PMID 21660237, 2011). "We were able to show that caveolin-1 protein expression is a predictor of poor disease-free survival in clear cell RCC, suggesting that cell signaling pathways involving caveolin-1 may be of importance in tumor progression." (PMID 22152020, 2011). "There was heterogeneous staining for caveolin-1 in tumor emboli." (PMID 22093547, 2011). "Several important proteins involved in cell transformation and growth have been shown to interact with CAV1 including the molecules that stimulate tumor cell invasion and cytoskeletal rearrangement such as growth factor receptors, protein kinases, heterotrimeric G-proteins and Rho GTPases." (PMID 21471610, 2011). "Caveolin-1 function is thought to be interdependent on tumor stage and the expression of molecular effectors that may have an impact on its role during tumor progression." (PMID 21660237, 2011). "Caveolin-1 appears to act as a tumor suppressor protein at early stages of cancer progression." (PMID 21471610, 2011). "Numerous follow-up studies designed to test this hypothesis have contributed a myriad of evidence suggesting that CAV1 may indeed possess tumor suppressor capabilities." (PMID 22152020, 2011). "Moreover, Kaplan-Meier analysis disclosed significant differences in overall and tumor specific survival for patients with higher and lower than average cytoplasmic CAV1 expression levels, respectively." (PMID 22152020, 2011). "In contrast, using univariate analysis, high membranous CAV1 failed to significantly predict tumor associated death rates during follow up (42.9% vs. 33.6%, p = 0.25, Fisher's exact test)." (PMID 22152020, 2011). "Kaplan-Meier analysis disclosed significant differences in overall and tumor specific 5-year survival for patients with higher and lower than average cytoplasmic CAV1 expression levels, i.e. 51.4% vs. 75.2% for overall survival and 55.3% vs. 80.1% for disease specific survival, respectively." (PMID 22152020, 2011). "Evaluation of the expression status of both CAV1 and mTOR pathway components in these tumors may help to predict tumor response to novel pathway specific therapies, hence allowing appropriate selection of treatment for individual patients." (PMID 22152020, 2011). "CAV1 is likely to be a useful prognostic marker and may play an important role in tumour progression." (PMID 22152020, 2011). "Accordingly, neither overall nor tumor specific Kaplan-Meier survival were significantly associated with CAV1 expression located in the tumor cell membranes (p = 0.41 and 0.24, respectively)." (PMID 22152020, 2011). "By acting as a scaffolding protein, Cav-1 plays crucial roles in the regulation of various physiologic and patho-physiologic processes including oncogenic transformation and tumorigenesis, and tumor invasion and metastasis." (PMID 20700465, 2010). "Our results may provide a possible explanation for the differential expression of Cav-1 at various stages of tumor progression." (PMID 20700465, 2010). "Recently,based on the unbiased proteomic and transcriptional analysis of Cav-1 (-/-)stromal cells, we have proposed that tumor stromal fibroblasts may undergoaerobic glycolysis." (PMID 20442453, 2010). "Forced expression of Cav-1 inhibits tumor growth and induces apoptosis of tumor cells." (PMID 20700465, 2010). "Functional role of Cav-1 appears to differ depending on the tumor cell type and/or tumor stage." (PMID 19239691, 2009).
tumor (continued). "Also, caveolin-1 is highly expressed in tumor cells more than their peritumoral cirrhotic regions in HCC tissues." (PMID 19239691, 2009). "Whether this observation reflects merely the superimposition of two tumor suppressor mechanisms, or CAV1 can interact synergistically with RES remains to be clarified." (PMID 19321006, 2009). "It was shown that differences in Cav-1 expression depend on the type of tumor cells." (PMID 19239691, 2009). "Also, caveolin-1 expression in the tumor cells was significantly stronger than the cells in surrounding tissue when analysed all HCC samples (p < 0.001)." (PMID 19239691, 2009). "CAV1, a member of Caveolin family may represent a tumor suppressor abolishing anchorage-independent growth of transformed cells and it is poorly expressed in HCC." (PMID 19321006, 2009). "Caveolin-1 is the main component of caveolae membrane structures and has different roles during tumorigenesis in different cancer types with varying expression profiles, indicating that the role of caveolin-1 varies according to tumor type." (PMID 19239691, 2009). "Collectively, these data demonstrate that patients who had tumours that coexpressed caveolin-1 and an activated AKT/mTOR pathway have significantly shorter recurrence-free survival than those patients who had tumours that expressed caveolin-1 alone or activated AKT/mTOR components alone." (PMID 18283322, 2008). "Overexpression of Cav-1 suppressed growth of the CavS tumours compared with the EV tumours." (PMID 19002186, 2008). "Thus, this study was designed to examine the effect of Cav-1 overexpression on tumour progression and metastasis potential of HNSCC." (PMID 19002186, 2008). "Thus by using this highly metastasis xenograft mouse model, we were able to show that restoration of Cav-1 protein expression substantially reduced tumour growth and inhibited lung metastasis." (PMID 19002186, 2008). "However, we were able to assess the dynamic changes in Cav-1 protein expression during metastasis by performing pairwise comparisons of Cav-1 expression levels between primary tumours and LNM from the same patient." (PMID 19002186, 2008). "Evaluation of the expression status of both caveolin-1 and mTOR pathway components in these tumours may help predict tumour response to novel pathway-specific therapies, hence allowing appropriate selection of treatment for individual patients." (PMID 18283322, 2008). "There is a significantly higher percentage of tumor associated endothelial cells (TAEC) in cav-1 positive tumors than in cav-1 negative tumors." (PMID 19763245, 2008). "Whether caveolin-1 acts to prevent or promote tumour development appears to depend on the cellular context." (PMID 18400052, 2008). "The interplay of Cav-1 with integrins could modulate integrin-dependent tumour cell growth and invasion." (PMID 19002186, 2008). "Since caveolin-1 and the AKT/mTOR signalling cascade are independently shown to be important regulators of tumour angiogenesis, we hypothesised that caveolin-1 interacts with the AKT/mTOR pathway to drive disease progression and metastasis in RCC." (PMID 18283322, 2008). "Thus, while it is clear that caveolin-1 function in tumour cells depends on the cellular context, the precise molecular determinants that define how one set of characteristics prevails over the other remain essentially undefined." (PMID 18400052, 2008). "Caveolin-1 has been observed to be down-regulated in a number of tumours and tumour cell lines." (PMID 18949068, 2007). "The greater induction of caveolin-1 compared with p27 in vivo may reflect pharmacologic barriers preventing the drug from reaching all of the tumor cells in vivo." (PMID 17764562, 2007). "For example, it has been shown to repress the transcription of cyclin D1, which is required for cell cycle progression, and increased cyclin D1 expression was shown to be the main reason for the increased tumour formation in tumour prone caveolin-1 knockout mice." (PMID 18949068, 2007).